ICAM1 (intercellular adhesion molecule 1)
Diseases named in the same sentence as ICAM1 in open-access papers (continued):
Sharing a sentence is not in itself a finding about the gene and the disease.
endothelial dysfunction (continued). "In physiological condition, ICAM-1 keeps very low level in circulation, but its level may markedly elevate during endothelial dysfunction." (PMID 34326842, 2021). "Fish long-chain omega-3 PUFA helped to protect against vascular risk factors such as inflammation, endothelial dysfunction (with reduced circulating markers such as VCAM-1, E-selectin, and ICAM-1), and vascular resistance (i.e., improve flow-mediated arterial dilation)." (PMID 33718454, 2021). "Therefore, VCAM-1, ICAM-1, and E-selectin are considered as important markers of endothelial dysfunction." (PMID 34123418, 2021). "sTREM-1 levels positively correlated with biomarkers for endothelial dysfunction (ICAM-1, VCAM-1, and E-selectin) and lactate level as well as clinical severity index (maximum 24 h APACHE score and Sequential Organ Failure Assessment (SOFA) score) upon admission." (PMID 34829326, 2021). "In addition, the sTREM-1 level is positively correlated with biomarkers for endothelial dysfunction (ICAM-1, VCAM-1, and E-selectin) and lactate level, clinical severity index (the maximum 24 h APACHE score and maximum 24 h SOFA score) upon admission." (PMID 34829326, 2021). "The gene transcription levels of von Willebrand factor (vWF), endothelin (ET), thrombomodulin (THBD), granular membrane protein 140 (GMP140), and intercellular cell adhesion molecule-1 (ICAM-1) related to endothelial dysfunction were all significantly increased." (PMID 34576058, 2021). "In addition, the higher the HDL-c level, the greater the protective effect against endothelial dysfunction based on ICAM-1 (OR = 0.95, 95% CI 0.90–0.99)." (PMID 32433661, 2020). "In addition, expression of VCAM-1, ICAM-1, P-selectin or pNF-κB are induced during inflammation by several stimuli, and these molecules facilitate transmigration of leukocytes during endothelial dysfunction." (PMID 32470058, 2020). "Finally, CAF feeding also resulted in increased levels in markers of endothelial dysfunction (ICAM-1, p = 0.041), arterial stiffness (Neuraminidase, p < 0.001), and inflammation (MCP-1, p < 0.001)." (PMID 31963315, 2020). "Increased CRP and reactive oxygen species (ROS) could trigger endothelial dysfunction that can increase the levels of ICAM-1 and VCAM-1, leading to increased monocyte chemoattraction, binding to LDL-molecules and increased risk for cardiovascular disease." (PMID 33269023, 2020). "Mitochondrial enzyme arginase type II (Arg-II) is reported to lead to endothelial dysfunction and enhance the expression of endothelial inflammatory adhesion molecules such as intercellular adhesion molecule-1 (ICAM-1) and vascular cell adhesion molecule-1 (VCAM-1)." (PMID 31474872, 2019). "Although one of the best documented roles of ICAM-1 is that of a mediator of leukocyte recruitment during atherosclerotic plaque formation, also being a marker, in its soluble form, of endothelial dysfunction and inflammation, its role has expanded to the inflammatory response in obesity and the AT." (PMID 31627295, 2019). "Des-fluoro-anacetrapib treatment was also associated with decreased bypass grafting-induced endothelial expression of vascular cell adhesion molecule-1 (VCAM-1) and intercellular adhesion molecule-1 (ICAM-1), endothelial dysfunction, and smooth muscle cell (SMC) proliferation in the grafted vein." (PMID 31700015, 2019). "We hypothesized that altitude-related endothelial dysfunction would lead to progressive shedding of ICAM-1, VCAM-1 and VE-cadherin into plasma." (PMID 31369589, 2019). "Complementary experiments to measure plasma biomarkers of inflammation, oxidative stress, and endothelial dysfunction such as resistin, ICAM-1, VCAM-1, and E-selectin could be useful to refine the mechanism of action of MOI." (PMID 31214278, 2019).
endothelial dysfunction (continued). "Another recent study showed that components of the IL-6 trans-signaling system were significantly elevated in more than 200 subjects with MetS and positively correlated with markers of endothelial dysfunction and arterial stiffness, such as E-selectin, ICAM-1 and VCAM-1." (PMID 31550292, 2019). "Higher levels of ICAM-1, VCAM-1 and E-Selectin might be very useful in predicting patients at high risk of endothelial dysfunction, especially in the case of SCD patients with VOC, in this study." (PMID 29690499, 2018). "In Ghana, studies have been done in the area of epidemiology of SCD and its complications, but there is no report on the possible association between endothelial cell adhesion molecules (VCAM-1, ICAM-1 and E-Selectin) and endothelial dysfunction in SCD patients." (PMID 29690499, 2018). "Studies of endothelial dysfunction further showed elevated blood levels of the intercellular adhesion molecule ICAM1 in patients with lacunar infarctions, whereas VCAM1 and P-selectin were increased in cases with WMLs at the periventricular region but not at deep subcortical locations." (PMID 30470258, 2018). "Moreover, we showed that the new LSM of the modified system was more effective than the traditional system in preventing TNF-α-induced endothelial dysfunction based on qPCR of ICAM-1, HO-1, and PAI-1 gene levels." (PMID 29354066, 2017). "Recruitment of inflammatory cells by ICAM-1 may result in destruction of aorta wall leading to aneurysm formation, suggesting a role for ICAM-1 in the initiation of endothelial dysfunction and aneurysm formation." (PMID 28069066, 2017). "The increased expression of ICAM1 may reflect endothelial dysfunction or microvascular inflammation; ICAM1 expression is recognized mainly in the endothelial cells but can also be found in microglia and leukocytes." (PMID 28655874, 2017). "With regard to future directions, it would be of interest to support our findings with measuring markers of endothelial dysfunction, such as adhesion molecules (i.e., intracellular adhesion molecule 1, ICAM-1), cytokines (interleukin 6, IL-6), matrix metalloproteinases." (PMID 28918499, 2017). "Additionally, preeclamspia plasma mediators increased endothelial dysfunction as evident from the significant increase in gene expression of ICAM-1 (3.92 ± 0.51 fold, n = 8, P < 0.01) in HUVEC respectively, compared to uncomplicated pregnancy." (PMID 27604418, 2016). "The ARIC study only observed a positive association between high levels of ICAM-1 and T2D with high levels of oxidized LDL providing evidence for the hypothesis that endothelial dysfunction needs the presence of oxidative stress to alter T2D risk." (PMID 27013319, 2016). "The HR (95 % CI) for T2D for biomarkers of endothelial dysfunction ICAM-1 and E-selectin for Q4 v." (PMID 27013319, 2016). "Moreover, isocarbophos remarkably induced endothelial dysfunction in the middle cerebral artery and the expressions of ICAM‐1 and VCAM‐1 in the posterior cerebral artery." (PMID 26818681, 2016). "Furthermore, 5-MTP reduced endothelial loss and detachment, ICAM-1 and VCAM-1 expressions, and inflammatory cell infiltration in the ligated arterial wall, suggesting attenuation of endothelial dysfunction." (PMID 27146795, 2016). "A widely popular definition of the endothelial dysfunction includes overexpressing adhesion molecules such as ICAM-1, VCAM-1, E-selectin, and P-selectin in the vascular endothelium as well as physiological changes such as flow-mediated vasodilatation (FMD) or forearm blood flow (FBF)." (PMID 24829798, 2014). "Similarly, higher AF was detected in patients with endothelial dysfunction expressed by vWF, ICAM-1, and VCAM-1." (PMID 23671885, 2013). "Regarding endothelial dysfunction (ED), vWF, ICAM-1, and VCAM-1 were selected as indicators." (PMID 23671885, 2013).
endothelial dysfunction (continued). "Moreover, endothelial dysfunction as an early marker of DR is also present in obesity and is characterised by increased levels of intracellular adhesion molecule-1 (ICAM-1)." (PMID 24347825, 2013). "Furthermore, I/R induce production of reactive oxygen species, promoting endothelial dysfunction and upregulation of ICAM-1 and P-selectin." (PMID 22558345, 2012). "Both ET-1 and ICAM-1 are considered to be important markers of endothelial dysfunction." (PMID 21871109, 2011). "Recently, microvascular endothelial inflammation has also gained clinical importance in mediating endothelial dysfunction by reducing coronary flow reserve and myocardial perfusion in HFpEF patients via increased expression of endothelial adhesion molecules like ICAM-1 and VCAM-1." (PMID 40072053, 2025). "Furthermore, our findings revealed that biomarkers reflecting fibroproliferative processes (VEGF, uPAR, galectin-3, E-selectin, and surfactant protein D), endothelial dysfunction (ANG-2, PECAM-1, and ICAM-1), and D-dimer were also associated with increased mortality risk." (PMID 41217548, 2025). "N. sativa seems beneficial in attenuating VCAM-1 and ICAM-1 levels under different situations; however, additional long-term controlled clinical trials are needed for making concise conclusions about the effect of N. sativa on endothelial dysfunction related biomarkers." (PMID 40365513, 2025). "Furthermore, IL-6 upregulates vascular cell adhesion molecule-1 (VCAM-1) and intercellular adhesion molecule-1 (ICAM-1), facilitates T-cell differentiation, and enhances angiotensin II type 1 receptor expression in SMCs, exacerbating oxidative stress and endothelial dysfunction." (PMID 41375637, 2025). "Additionally, a reduction in biochemical markers intracellular adhesion molecule-1 (ICAM-1) and endothelin-1 (ET-1) were seen in the intervention group, both indicators of inflammation and endothelial dysfunction, further supporting the proposed mechanism of action of ischaemic conditioning." (PMID 39702489, 2024). "It has been demonstrated that the soluble molecules VCAM-1, ICAM-1, and E-selectin were associated with the risk of mortality in an SCD cohort and are also correlated with the severity of pulmonary hypertension, a clinical manifestation of endothelial dysfunction." (PMID 38153527, 2024). "In addition, RSV increased total antioxidant capacity and downregulated endothelial dysfunction biomarkers, such as intercellular adhesion molecule-1 (ICAM-1), von Willebrand factor (vWF), and Caspase-3, (CASP-3), in endothelial cells and umbilical arteries from PE patients." (PMID 36358483, 2022). "In addition, ADM has been shown to reduce the expression of endothelial dysfunction biomarkers such as intercellular adhesion molecule-1 (ICAM-1) and vascular adhesion molecule-1 (VCAM-1), and inflammatory factors in lymphatic endothelium and VEGF-stimulated human umbilical vein endothelial cells." (PMID 36362188, 2022). "In addition, possible RSV-driven modulation of endothelial dysfunction markers was investigated, including intercellular adhesion molecule-1 (ICAM-1), von Willebrand factor (vWF), and Caspase-3, (CASP-3), in endothelial cells and umbilical arteries from patients with PE." (PMID 36358483, 2022). "Moreover, resistin causes endothelial dysfunction by enhancing proinflammatory markers such as MCP-1, TNF-α, IL-6, long pentraxin 3, IL-1β, vascular cell adhesion molecule-1 (VCAM-1), and intercellular adhesion molecule-1 (ICAM-1)." (PMID 35177953, 2022). "Additionally, the measurement of vWF, s-ICAM-1 and sCD-40L might be suggested in patients with heart failure to confirm endothelial dysfunction and provide personalized therapy." (PMID 35886486, 2022).
endothelial dysfunction (continued). "Our data support the hypothesis that a short period of 6 months is insufficient to induce morphological changes in the carotid wall, but that such interventions can produce improvements in the serological markers of endothelial dysfunction, such as ICAM-1, and in the lipid-based atherogenic indices." (PMID 35010908, 2021). "In addition, long-chain n-3 PUFA may play an important role in improving the endothelial function, lowering circulating markers of endothelial dysfunction, such as E-selectin, vascular cell adhesion molecule-1 and intercellular adhesion molecule-1." (PMID 34371852, 2021). "In this study, quercetin could inhibit LPS-induced attachment of monocytes to HUVECs by downregulating expressions of VCAM-1 and ICAM-1 in vitro as well as suppress the expression of pro-inflammatory cytokines, which demonstrated the ability of quercetin to ameliorate endothelial dysfunction." (PMID 33425996, 2020). "However, our recent studies suggest that hypoglycosylated or high mannose (HM)-ICAM-1 N-glycoforms are also expressed on the cell surface during endothelial dysfunction, and have higher affinity for monocyte adhesion and regulate outside-in endothelial signaling by different mechanisms." (PMID 32208424, 2020). "As endothelial dysfunction may trigger inflammation and is closely linked with vascular pathology, including peripheral vascular calcification, we investigated normal (CD31, CD105, vWF) and activated (ICAM‐1) endothelial markers." (PMID 30868685, 2019). "In turn, ICAM-1 and E-selectin participate in the regulation of inflammatory processes and may affect the pathology of endothelial dysfunction by activation of neutrophils and monocytes; their activity is also related to increased concentration of pro-inflammatory cytokines like TNF-α and MCP-1." (PMID 28959007, 2017). "Similarly, the current study also demonstrated that serum ICAM-1 levels were inversely related to lowest PaO2/FiO2, suggesting that endothelial dysfunction may be the reason of lung injury." (PMID 26381483, 2015). "Impaired NO production and upregulation of adhesion molecules such as P-selectin and intercellular adhesion molecule 1 (ICAM-1) enhance leukocyte adhesion and infiltration into the myocardium, demonstrating endothelial dysfunction." (PMID 40722608, 2025). "We confirmed successful induction of endothelial dysfunction by confirming the upregulation of VCAM1 (P = 0.0031 at 10 ng/mL TNFα), ET-1 (P = 0.0034 at 10 ng/mL TNFα) and ICAM1 (P = 0.0014 at 10 ng/mL TNFα)." (PMID 40234537, 2025). "Elevated levels of soluble ICAM-1 (sICAM-1) and soluble VCAM-1 (sVCAM-1) have been identified as biomarkers of endothelial dysfunction." (PMID 40299499, 2025). "Our data show that exposure to DEPs increased the concentrations of ICAM-1, VCAM-1, E-selectin and P-selectin in the plasma, and that nerolidol administration effectively prevented the rise in these markers of endothelial dysfunction." (PMID 40149705, 2025). "Oxidative stress markers, such as malondialdehyde (MDA), along with endothelial dysfunction markers like vascular endothelial growth factor (VEGF) and intercellular adhesion molecule-1 (ICAM-1), play a crucial role in the pathophysiology of DFUs." (PMID 40364880, 2025). "The reduction of VEGF and increase of ICAM-1 and VECD in the AMD rats suggests the presence of endothelial dysfunction in the model rats." (PMID 40860876, 2025). "These substances, in turn, stimulate the production of endothelial CCL2, ICAM-1, and VCAM-1, which exacerbate endothelial dysfunction." (PMID 40943241, 2025). "Induces pro-inflammatory signaling in endothelial cells, upregulates adhesion molecules (ICAM-1, VCAM-1), and decreases NO production, worsening endothelial dysfunction." (PMID 40529825, 2025). "The increase in soluble forms of adhesion molecules, ICAM-1 and VCAM-1, is an indicator of immune system activation and endothelial dysfunction." (PMID 40217768, 2025).
endothelial dysfunction (continued). "Neurovascular integrity markers VCAM-1, ICAM-1, and VEGF were significantly elevated in diabetic rats, indicating endothelial dysfunction." (PMID 40723442, 2025). "TNF-α, by activating NF-κB signalling, increasing ROS production and up-regulating adhesion molecules, including ICAM-1 (Intercellular Adhesion Molecule-1) and VCAM-1 (Vascular Cell Adhesion Molecule-1), induces endothelial dysfunction." (PMID 41301783, 2025). "The anti-inflammatory effects of polygodial are varied, including the inhibition of Intercellular adhesion molecule 1 (ICAM1) and Vascular cell adhesion molecule 1 (VCAM1), which are involved in endothelial dysfunction." (PMID 40286191, 2025). "Endothelial dysfunction markers (VCAM-1, ICAM-1, sICAM-1/sVCAM-1),platelet activation (P-selectin), clotting factors (D-dimer, fibrinogen),hs-CRP (chronic inflammation), homocysteine (vascular stress marker)." (PMID 41031540, 2025). "It induces the expressions of ICAM-1 and VCAM-1, helps reduce the interaction among endothelial cells, and accelerates the progression of inflammation and endothelial dysfunction." (PMID 38195507, 2024). "Treatment of HUtMEC cells with recombinant s(P)RR resulted in increased levels of endothelial dysfunction markers; VCAM-1, ICAM-1, and ET-1, suggesting that elevated s(P)RR has the potential to cause systemic maternal endothelial dysfunction." (PMID 38605139, 2024). "This in turn reduces the levels of endothelial dysfunction markers such as vascular cell adhesion molecule 1 (VCAM‐1), intercellular adhesion molecule 1 (ICAM‐1), and E‐selectin." (PMID 38405061, 2024). "PA also triggered inflammation and endothelial dysfunction, as evidenced by NLRP3 activation, upregulation of ICAM-1 (endothelial activation marker), and pyroptotic markers (NLRP3, GSDM-D, IL-1β, IL-18)." (PMID 39770410, 2024). "The elevated levels of VEGFR2, ICAM-1, VCAM-1, and other less common vascular-related molecules further support the involvement of endothelial dysfunction and vascular activation in DME." (PMID 39685883, 2024). "Our study demonstrated that PA-induced endothelial dysfunction significantly increased expressions of NLRP3, ICAM-1, GSDM-D, and pro-inflammatory cytokines IL-1β and IL-18 in the HUVECs during PA-induced pyroptosis." (PMID 39770410, 2024). "These markers include indicators of endothelial dysfunction (VCAM-1, ICAM-1, MCP-1) and an acute-phase reactant (CRP)." (PMID 39144845, 2024). "Differently, the other cluster had high levels of serum occludin, IL-6R, soluble intercellular adhesion molecule-1 (sICAM-1) and VEC, with potential inflammatory-induced endothelial dysfunction." (PMID 39182041, 2024). "Meanwhile, the increased mRNA expression levels of endothelial dysfunction markers, VCAM-1 and ICAM-1, were decreased in ISL-treated db/db mouse aortas, further confirming that ISL reverses T2D-induced endothelial dysfunction." (PMID 39339760, 2024). "Encouragingly, ISL treatment significantly decreased the expression levels of VCAM-1 and ICAM-1 in db/db mouse aortas, further demonstrating that ISL reverses endothelial dysfunction in T2D mouse aortas." (PMID 39339760, 2024). "Seldin and collaborators show that primary HAECs treated with TMAO express higher levels of ICAM-1 and E-selectin, prompting TMAO as an inducer of adhesion molecules involved in the late endothelial dysfunction." (PMID 36982880, 2023). "So, both ICAM-1 and VCAM-1 have been used as inflammation marker and endothelial dysfunction because the expression of both CAMs is enhanced by a variety of proatherogenic stimuli such as proinflammatory cytokines and reactive oxygen species." (PMID 37822716, 2023). "CER-001 infusion ameliorated systemic endothelial dysfunction by reducing VCAM-1 and ICAM-1 serum levels in both treated groups, with an increased effect of the two doses of ApoA-I complexes as emphasized at T6 time points." (PMID 37915050, 2023).